CCT3 (chaperonin containing TCP1 subunit 3)
Diseases named in the same sentence as CCT3 in open-access papers (continued):
Sharing a sentence is not in itself a finding about the gene and the disease.
glioblastoma (5 papers, 2021 to 2024). The most malignant astrocytic tumor (WHO grade IV). "Research: GlioblastomaAchievement: CCT3 expression was significantly elevated in glioblastoma." (PMID 36185198, 2022). "Glioblastoma tissue had significantly higher levels of CCT2, CCT3, CCT5, CCT6A, and CCT7 gene expression relative to healthy brain tissue." (PMID 36185198, 2022).
colon cancer (4 papers, 2017 to 2025). "Here, we were the first study to report that targeting CCT3 significantly inhibited colon cancer cells proliferation." (PMID 36313331, 2022). "We further explored the oncogenic roles of CCT3 in colon cancer by vitro assay." (PMID 36313331, 2022). "In colon cancer, knockdown of CCT3 inhibited cell proliferation." (PMID 36313331, 2022). "In summary, our results implied CCT3 as a potential biomarker for many tumors and CCT3 could be a new molecular target for colon cancer." (PMID 36313331, 2022). "After the stratification of colorectal adenocarcinoma patients according to their tumor location, we noticed that patients with colon tumors (122 for DFS and 136 for OS) and the overexpression of circ-CCT3 showed significantly shorter DFS intervals (p = 0.032) and OS intervals (p = 0.005)." (PMID 41153715, 2025).
head and neck squamous cell carcinoma (4 papers, 2021 to 2025). A squamous cell carcinoma that arises from any of the following anatomic sites: lip and oral cavity, nasal cavity, paranasal sinuses, pharynx, larynx, and salivary glands. "The GEO, Oncomine, and ALCAN databases were used to examine CCT3 expression in head and neck squamous cell carcinoma (HNSCC)." (PMID 36185198, 2022). "Meanwhile, the high expression of CCT3 also contributed to the progression of head and neck squamous cell carcinoma (HNSCC)." (PMID 36313331, 2022).
osteosarcoma (4 papers, 2018 to 2024). A usually aggressive malignant bone-forming mesenchymal neoplasm, predominantly affecting adolescents and young adults. "Furthermore, CCT3 is an important specific driver gene in osteosarcoma." (PMID 36185198, 2022).
cervical cancer (3 papers, 2022 to 2025). A primary or metastatic malignant neoplasm involving the cervix. "This regulation was associated with multiple pathways, with overexpression of FN1 significantly rescuing the inhibition of CESC cell proliferation caused by CCT3 knockdown, suggesting that CCT3 upregulation promotes cervical cancer progression through FN1." (PMID 39928781, 2025). "Another study showed that CCT3 expression is significantly elevated in cervical cancer tissues compared to adjacent normal tissues and is associated with HPV-16/18 infection, tumor grade, and positive lymph node status." (PMID 39928781, 2025). "GSEA analysis indicated that CCT3 promoted cell growth by means of regulating cell cycle, which was consist with the results in cervical cancer." (PMID 36313331, 2022).
Cirrhosis (3 papers, 2016 to 2019). A chronic disorder of the liver in which liver tissue becomes scarred and is partially replaced by regenerative nodules and fibrotic tissue resulting in loss of liver function. "Our data showed that serum CCT3 levels in patients with small tumors (≤2 cm) provided a sensitivity of 76.6 % when distinguishing small HCC from cirrhosis at a cut-off value of 46.5 pg/mL." (PMID 27390551, 2016). "In this study, high levels of plasma CCT3 protein were detected in HCC, and CCT3 had better sensitivity (87.3 %) than AFP (69.8 %) in differentiating HCC from cirrhosis." (PMID 27390551, 2016). "Expression of serum CCT3 in patients with HCC (330.98 ± 207.51 pg/mL) was significantly higher (P < 0.001) than in patients with cirrhosis (82.03 ± 96.53 pg/mL), or healthy controls (50.34 ± 27.27 pg/mL)." (PMID 27390551, 2016). "High levels of plasma CCT3 protein were detected in HCC, and CCT3 had higher sensitivity (87.3 %) than AFP (69.8 %) in differentiating HCC from cirrhosis when the cut-off value was selected at 46.5 pg/mL and 20 ng/mL, respectively (P < 0.05)." (PMID 27390551, 2016). "In this study, we investigated CCT3 and IQGAP3 at plasma levels in patients with HCC or cirrhosis and in healthy individuals, and evaluated their application in detecting small and AFP-negative tumors in patients with HCC." (PMID 27390551, 2016). "In the plasma of HCC patients, both CCT3 and IQGAP3 were significantly higher than in patients with cirrhosis and in healthy controls (P < 0.01)." (PMID 27390551, 2016). "Blood samples were collected from 126 HCC patients with HCC, 88 patients with cirrhosis and 50 healthy volunteers to detect plasma α-fetoprotein (AFP), CCT3 and IQGAP3 levels." (PMID 27390551, 2016). "In addition, plasma CCT3 and IQGAP3 from 38 AFP-negative HCC and 88 cirrhosis patients were analyzed." (PMID 27390551, 2016).
bladder cancer (2 papers, 2023 to 2025). "This study surveyed circular RNA CCT3 in bladder cancer (BCa)." (PMID 37833621, 2023).
esophageal cancer (2 papers, 2022). A primary or metastatic malignant neoplasm involving the esophagus. "CCT3 can also be considered as a potential candidate biomarker for therapeutic targets of esophageal cancer." (PMID 36185198, 2022).
fatty liver disease (2 papers, 2022 to 2024). A reversible condition wherein large vacuoles of triglyceride fat accumulate in liver cells via the process of steatosis. "We found an increase in CCT3 gene expression, which correlated with the severity of metabolic-associated fatty liver disease and the pathological stage of HCC." (PMID 35022268, 2022). "Interestingly, CCT3 expression was found to be upregulated in patients with lipid metabolism disorders (metabolic‐associated fatty liver disease and nonalcoholic steatohepatitis), as determined via analysis of publicly available data." (PMID 38363102, 2024). "However, the role of CCT3 in metabolic‐associated fatty liver diseases has not been fully elucidated and deserves further study." (PMID 38363102, 2024).
leukemia (2 papers, 2018 to 2022). A malignant (clonal) hematologic disorder, involving hematopoietic stem cells and characterized by the presence of primitive or atypical myeloid or lymphoid cells in the bone marrow and the blood. "As expected, knockdown of MLL-interactors with known essential functions, such as RFC1, SF3A3, or CCT3, led to growth inhibition in both MLL-fusion cells and MLL-wild-type leukemia cells." (PMID 29777171, 2018). "KEGG pathway analysis indicated that the CCT3 targeted genes were involved in the JAK-STAT3 signaling pathway, the Hippo signaling pathway, the WNT signaling pathway, and two pathways centralizing in leukemia-related terms (namely acute myeloid leukemia and chronic myeloid leukemia)." (PMID 36185198, 2022).
lung squamous cell carcinoma (2 papers, 2022 to 2025). "Clinical relevance of CCT3 in LUAD and lung squamous cell carcinoma (LUSC) was analyzed based on TCGA database." (PMID 35773623, 2022).
melanoma (2 papers, 2022 to 2025). A malignant, usually aggressive tumor composed of atypical, neoplastic melanocytes. "The tumor-inhibiting functions of CCT3 silencing in melanoma were associated with CDK1 downregulation in the cell cycle signaling pathway, which might provide novel markers and targets for melanoma diagnosis and treatment." (PMID 35399722, 2022). "The results indicated that CCT3 highly expressed in melanoma tissues, and CCT3 overexpression is correlated with clinical stage in melanoma patients." (PMID 35399722, 2022). "CCT3 was highly expressed in melanoma tissues, thus, it was inferred to promote growth and inhibit the apoptosis of melanoma cells." (PMID 35399722, 2022). "In summary, our results demonstrated that CCT3 silencing greatly promoted apoptosis and interrupted the cell cycle progression of melanoma cells." (PMID 35399722, 2022). "Knockdown of CCT3 by shRNA in melanoma cells inhibited cell proliferation and cell cycle progression and induced cell apoptosis in vitro." (PMID 35399722, 2022). "Tumors treated with LV-shCCT3 exhibited significantly impaired staining of CCT3 compared with the control groups, suggesting that CCT3 knockdown inhibited melanoma cell tumorigenicity in vivo." (PMID 35399722, 2022). "In general, these findings indicated that CCT3 knockdown dramatically inhibits melanoma cell proliferation in vitro." (PMID 35399722, 2022). "In conclusion, our data demonstrated that CCT3 plays an important role in the development and progression of melanoma." (PMID 35399722, 2022). "A tissue microarray of 40 melanoma patients with paired adjacent counterparts was evaluated for the expression of CCT3 protein by IHC." (PMID 35399722, 2022). "we demonstrated CCT3 was highly expressed in melanoma specimens compared with adjacent tissues, and the level of CCT3 is correlated with the clinical stage in melanoma patients." (PMID 35399722, 2022). "In this report, our study presented the first report on the tumor-promoting effect of CCT3 in melanoma cells." (PMID 35399722, 2022). "In this study, we explored the expression of CCT3 in patients with melanoma and investigated its effects on melanoma cell proliferation, apoptosis and cell cycle progression and its potential mechanisms in vita by silencing the CCT3 gene." (PMID 35399722, 2022). "Melanoma xenograft mouse models were employed to investigate the effects of CCT3 silencing on tumorigenicity in vivo." (PMID 35399722, 2022). "Knockdown of CCT3 expression in the melanoma cells suppresses cell proliferation and cell cycle progression and promote apoptosis." (PMID 35399722, 2022). "In the present study, exploring the potential mechanism by which CCT3 may be involved in melanoma was attempted through IPA analysis." (PMID 35399722, 2022). "Cellular functions of CCT3 in melanoma cells were explored by CCT3 knockdown to verify our hypothesis." (PMID 35399722, 2022). "Here we elucidate the functional contribution to CCT3 to melanoma progression." (PMID 35399722, 2022). "Despite the adverse effect of CCT3 on the progression of different solid tumors, the involvement of CCT3 in the tumorigenesis of melanoma remains unknown." (PMID 35399722, 2022). "CDK1 can serve as a potential downstream target of CCT3 in melanoma." (PMID 35399722, 2022). "Therefore, our results indicated that CCT3 knockdown can significantly inhibit the development of melanoma." (PMID 35399722, 2022). "MTT assay also showed that decreased cell proliferation due to CCT3 silencing was rescued by CDK1 overexpression (P < 0.001), suggesting that CDK1 may serve as a downstream effect of CCT3 on tumor cell growth in melanoma." (PMID 35399722, 2022). "However, only CDK1 was selected for this research, whether the other four genes in WB verification were functionally regulated by CCT3 in melanoma cells needs further and in-depth study." (PMID 35399722, 2022).
melanoma (continued). "Overall, our findings suggest that CCT3 depletions prohibited melanoma progression by downregulating CDK1 expression and is a potential therapeutic target for melanoma." (PMID 35399722, 2022). "Then, these results may imply that CCT3 silencing regulates the expression of CDK1, and affects the process of the cell cycle, resulting in the inhibition of proliferation of melanoma cells." (PMID 35399722, 2022).
non-small cell lung carcinoma (2 papers, 2022). A group of at least three distinct histological types of lung cancer, including non-small cell squamous cell carcinoma, adenocarcinoma, and large cell carcinoma. "speculated that CCT3 may be closely involved in the tumorigenesis and progression of non-small cell lung cancer (NSCLC), and it might have a more prominent role in LUAD." (PMID 36185198, 2022).
ovarian carcinoma (2 papers, 2016 to 2022). A malignant neoplasm originating from the surface ovarian epithelium. "CCT3 is significantly associated with carboplatin resistance in ovarian cancer patients after surgery treatment." (PMID 27818681, 2016). "Research: Ovarian cancerAchievement: CCT3 is an effective marker for ovarian cancer." (PMID 36185198, 2022). "experimentally identified several potential novel biomarkers for ovarian cancers, including CCT3." (PMID 36185198, 2022).
prostate carcinoma (2 papers, 2022). A carcinoma that arises from epithelial cells of the prostate gland. "In agreement with this study, CCT3 suppression led to oxidative stress and energy deficiency in breast and prostate cancer." (PMID 36313331, 2022). "Research: Breast and prostate cancersAchievement: CCT3 suppression prompts apoptotic machinery through oxidative stress and energy deprivation in breast and prostate cancers." (PMID 36185198, 2022). "And CCT3 is responsible for castration-resistant prostate cancer." (PMID 36313331, 2022).
tongue squamous cell carcinoma (2 papers, 2020 to 2021). A squamous cell carcinoma that arises from the tongue. "In Estilo’s study and Talbot’s study, CCT3 was also overexpressed in tongue squamous cell carcinoma with fold changes of 2.143 and 2.117, respectively." (PMID 33313411, 2020).
brain malformations (1 paper, 2025). "Recent reports provide evidence for presence of variants in several TRiC/CCT members including CCT1, CCT3, CCT5, CCT6A, CCT7 and CCT8, in brain malformations, seizures, and intellectual disability." (PMID 40779003, 2025).
breast adenocarcinoma (1 paper, 2022). "The mimic transfection of miR-24-3p, miR-128-3p, and miR-149-5p suppressed the level of CCT3 in ductal-breast adenocarcinoma and prostate carcinoma cells, which induced G0/G1 phase arrest and disturbed the mitochondrial membrane potential, eventually triggering apoptosis." (PMID 35591858, 2022). "In ductal-breast adenocarcinoma cells, the expression of BAX was increased via suppressing CCT3 by miR-24-3p or miR-128-3p." (PMID 35591858, 2022).
Cerebral ischemia (1 paper, 2025). Restriction of arterial blood supply to the brain associated with insufficient oxygenation to support the metabolic requirements of the tissue. "Based on these findings, we hypothesize that the key target protein CCT3, modulated by NA, plays a critical role in attenuating oxidative stress during the therapeutic process for cerebral ischemia-reperfusion injury." (PMID 39936033, 2025). "Furthermore, our findings revealed additional proteins that may serve as biomarkers for cerebral ischemia-reperfusion injury, including STAT3, NME2, VCL, and CCT3." (PMID 39936033, 2025).
colorectal adenocarcinoma (1 paper, 2025). The most common type of colorectal carcinoma. "A previously developed, highly sensitive quantitative PCR (qPCR) assay was applied to determine circ-CCT3 expression in 216 primary colorectal adenocarcinoma tissue specimens and 86 paired normal colorectal tissues." (PMID 41153715, 2025). "Colorectal adenocarcinoma patients with circ-CCT3 overexpression were shown to have significantly lower DFS probabilities (p < 0.001), compared to patients with lower circ-CCT3 levels." (PMID 41153715, 2025). "Higher circ-CCT3 expression was associated with a poorer disease-free (DFS) and overall survival (OS) of colorectal adenocarcinoma patients." (PMID 41153715, 2025). "In this study, we examined whether circ-CCT3 expression can predict the prognosis of patients diagnosed with colorectal adenocarcinoma, the most frequent type of CRC." (PMID 41153715, 2025). "Furthermore, low circ-ABCC1 expression was associated with tumor growth and disease progression, while the overexpression of circ-PRMT1 in colorectal adenocarcinoma has very recently been shown to predict recurrence and poor OS, similarly to circ-CCT3." (PMID 41153715, 2025). "Additionally, the unfavorable prognostic value of circ-CCT3 overexpression was observed in Kaplan–Meier OS analysis, which revealed that colorectal adenocarcinoma patients with circ-CCT3 overexpression had significantly poorer OS (p < 0.001)." (PMID 41153715, 2025). "circ-CCT3 overexpression was shown to retain its unfavorable prognostic significance regarding DFS, independently of other established prognostic factors in colorectal adenocarcinoma (HR = 1.75; p = 0.039)." (PMID 41153715, 2025). "Moreover, the receiver operating characteristic (ROC) curve analysis demonstrated that the circ-CCT3 expression may very efficiently distinguish colorectal adenocarcinoma from normal colorectal mucosa [area under the ROC curve (AUC) = 0.92, 95% CI = 0.89–0.95, p < 0.001]." (PMID 41153715, 2025). "Results: circ-CCT3 was significantly upregulated in colorectal adenocarcinoma tissues, in comparison to their non-cancerous tissue counterparts." (PMID 41153715, 2025). "Next, we investigated whether there was any correlation between circ-CCT3 expression and the DFS and/or the OS of colorectal adenocarcinoma patients." (PMID 41153715, 2025).
COVID-19 (1 paper, 2025). A disease caused by infection with severe acute respiratory syndrome coronavirus 2. "Remarkably, telomere maintenance processes were observed to be one of the top biological processes activated in patients with mild COVID-19 via activation of genes such as CCT2, CCT3, CCT4, CCT5 and CCT6A." (PMID 41141600, 2025).
craniosynostosis (1 paper, 2018). Craniosynostosis is defined as the premature fusion of one or more cranial sutures leading to secondary distortion of skull shape resulting in skull deformities with a variable presentation. "Out of seven genes with a high (< 10%) or moderate (< 25%) HI score (NES, CCT3, MEF2D, LAMTOR2, ETV3, SSR2, NTRK1), none of them have been linked to craniosynostosis." (PMID 29845577, 2018).
cutaneous melanoma (1 paper, 2022). A primary melanoma arising from atypical melanocytes in the skin. "Furthermore, the expression level of CCT3 was detected in three cutaneous melanoma cell lines." (PMID 35399722, 2022).
diabetic nephropathy (1 paper, 2025). "CCT3 may be a marker of diabetic nephropathy and KRT8 has been shown to be involved in the regulation of blood glucose." (PMID 40502754, 2025).
glioma (1 paper, 2025). A benign or malignant brain and spinal cord tumor that arises from glial cells (astrocytes, oligodendrocytes, ependymal cells). "Moreover, analyses of gene expression and DNA copy number showed that CCT2, CCT3, CCT5, CCT6A, and CCT7 are upregulated in GBM compared with normal brain tissue, while CCT2, CCT3, CCT5, CCT6A, and CCT8 display higher copy numbers than in low-grade gliomas." (PMID 41516249, 2025).
kidney chromophobe (1 paper, 2023). "However, CCT3 mRNA was also found to be downregulated in tumor tissues of kidney chromophobe (KICH) and kidney renal clear cell carcinoma (KIRC)." (PMID 36918801, 2023).
lipid metabolism disorders (1 paper, 2022). "Since these assays confirmed that alteration of CCT3 and LINC00326 gene expression levels modulate regulation of lipid metabolism, we inspected publicly available data from patient liver biopsies with lipid metabolism disorders (GSE126848 and TCGA)." (PMID 35022268, 2022).
Parkinson disease (1 paper, 2025). A progressive degenerative disorder of the central nervous system characterized by loss of dopamine producing neurons in the substantia nigra and the presence of Lewy bodies in the substantia nigra and locus coeruleus. "Here, we show that the apical domains of subunits CCT3 and CCT7 from humans are strong inhibitors of tau aggregation, which is associated with several neurological disorders such as Alzheimer's and Parkinson's diseases." (PMID 40400346, 2025).
Renal neoplasm (1 paper, 2023). The presence of a neoplasm of the kidney. "Thus, the pan-cancer dysregulation of CCT3 occurs in an opposite direction and future research focused on CCT3 downregulation in renal neoplasm will facilitate a better understanding of CCT3 effects in malignancy." (PMID 36918801, 2023).
retinal degeneration (1 paper, 2019). Degeneration of the retina. "Similar to our cct5 mutant, cct1, cct2, cct3, cct4 and cct8 mutant zebrafish show retinal degeneration, suggesting that the cct5/tcf7l1a double mutant phenotype is due to abrogation of TRiC chaperonin function, a conclusion supported by cct3 knockdown in tcf7l1a mutants." (PMID 30777146, 2019).